CCNE1 (cyclin E1)
Diseases named in the same sentence as CCNE1 in open-access papers (continued):
Sharing a sentence is not in itself a finding about the gene and the disease.
serous ovarian cancer (continued). "Nine of our 15 tumors (60%) showed CCNE1 copy number gains while data from TCGA (509 high grade serous ovarian carcinomas) presented CCNE1 gains in 32.4% or focal amplification in 20.8%." (PMID 31060523, 2019). "Novel therapeutic targets that augment taxane effects are needed to improve clinical chemotherapy response in CCNE1-amplified high grade serous ovarian cancer (HGSOC) cells." (PMID 29899826, 2018). "Cyclin-dependent kinase 2 (CDK2) was reported as an ideal target for high-grade serous ovarian cancer (HGSC) with elevated CCNE1 expression." (PMID 29433585, 2018). "Recent genomic analyses have identified cyclin E1 gene amplification as a candidate oncogenic driver in high-grade serous ovarian carcinoma." (PMID 25625291, 2015). "Amplification of the cyclin E1 gene (CCNE1, 19q12) is the key genetic event driving CCNE1 overexpression, occurring in approximately 20% of high grade serous ovarian carcinomas (HGSOC), 10–15% of uterine serous and carcinosarcoma cases, and 15% of clear cell carcinomas (CCOC)." (PMID 41331376, 2025). "Additionally, the Kaplan–Meier plot results revealed that increased expression of ATAD2, CCNE1, CDC20, and SMC4 was associated with poor survival in serous ovarian cancer patients (p < 0.05)." (PMID 39199556, 2024). "Likewise, CCNE1 was found to be amplified in serous ovarian cancer patients who had reduced response to chemotherapy and poor survival." (PMID 39199556, 2024). "CCNE1 is amplified in 8% of endometrial endometrioid adenocarcinomas (EMCAs), 45% of uterine carcinosarcomas, and 50% of serous EMCAs, particularly in high-grade serous ovarian cancer (HGSOC) and endometrial cancer (EC)." (PMID 36964635, 2023). "Early clinical data of the combination of checkpoint kinase inhibition and immune checkpoint blockade showed durable responses in several CCNE1 amplified patients with high grade serous ovarian cancers, suggesting an interplay between cell cycle inhibition, DNA damage repair and the immune response." (PMID 34485660, 2021). "Cyclin E1 dysregulation has further been reported to drive malignant transformation in fallopian tube secretory cells that are the site of origin of high-grade serous ovarian carcinomas." (PMID 25625291, 2015). "There is good evidence that CCNE1 is the correct call since Cyclin E is a key cell cycle protein and its amplification and over expression has been previously identified as a key driver of patient response to chemotherapy in serous ovarian carcinoma." (PMID 20844748, 2010). "In high-grade serous ovarian cancer cases, Cyclin E1 is connected with chromosomal instability, the overexpression of which is associated with an increased copy number of USP28, although the effect induced by alteration of USP28 is relatively weaker than CCNE1 (encodes Cyclin E1) amplification." (PMID 36879346, 2023). "Cyclin E1 is phosphorylated by CDK12 at Ser366 position and this brings about the upregulation of cyclin E1 in cancer cells, for instance in the high-grade serous ovarian cancer (HGSC)." (PMID 39318358, 2024). "CCNE1 gain is a common event in OCS, occurring more frequently than in high grade serous ovarian carcinoma (HGSOC)." (PMID 38097740, 2024). "It has been previously reported that CCNE1-amplification, which occurs in 15–20% of high-grade serous ovarian cancer (HGSOC) patient tumors, generally does not co-occur with loss of function mutations of HR genes." (PMID 37519629, 2023).
hepatocellular carcinoma (44 papers, 2013 to 2025). A malignant tumor that arises from hepatocytes. "Although the gene encoding the other subunit of CDK2, CCNE1, has been linked to poor prognosis in hepatocellular carcinoma (HCC), there is little known about the role of CCNE2 in tumor progression." (PMID 33869043, 2021). "HOXA7 promotes hepatocellular carcinoma through cyclin E1/CDK2, inducing proliferation, migration, colony formation, and tumorigenesis in vivo." (PMID 39596630, 2024). "Among them, INPP5F has been recently demonstrated to be an oncogene that activates the ASPH-mediated Notch-c-MYC/cyclin E1 pathway in hepatocellular carcinoma." (PMID 37469520, 2023). "Previous studies have shown that CDK6, CCND1 and CCNE1 play an important role in the proliferation of hepatoma cells." (PMID 34980127, 2022). "Cyclin E1 knockdown restores the sensitivity of sorafenib-resistant hepatocellular carcinoma cells to this drug." (PMID 36142752, 2022). "Numerous studies have indicated CCNA2 and CCNE1 play a central role in various types of malignancy such as hepatocellular carcinoma, breast, and colon cancer." (PMID 35625619, 2022). "Together, these findings demonstrated that SCUBE3 promotes proliferation of hepatoma cells through CCNE1." (PMID 34980127, 2022). "Our data suggest that overexpression of CCNE1 is a key driver of hepatocarcinogenesis by promoting several oncogenic events besides hepatoma cell proliferation in a CDK2-independent manner." (PMID 34830835, 2021). "miRNAs from multiple families have been identified to target CCNE1 in a number of malignant tumours, such as hepatocellular carcinoma, osteosarcoma, cervical cancer, and bladder cancer." (PMID 32962636, 2020). "The previous literature has confirmed that upregulation of CCNE1 occurs in human hepatocellular carcinomas." (PMID 32102682, 2020). "The initiation of hepatocellular carcinoma depends on E-type cyclins E1 (CcnE1) and cyclin-dependent kinase 2 (Cdk2)." (PMID 32570707, 2020). "In summary, the present work show that daphnegiravone D markedly suppress the proliferation and survival of hepatoma cells, and induce G0/G1 arrest by reducing the expression of cyclin E1, CDK2 and CDK4 in a p38-dependent manner." (PMID 28720813, 2017). "The suppression of ARID2 expression in hepatoma cells facilitated G1/S transition associated with transcriptional upregulation of E2F1, cyclin D1, and cyclin E1, induction of CDK4, and phosphorylation of Rb." (PMID 27351279, 2016). "For hsa_circ_0004315, some studies have found that this circRNA may act as a molecular sponge for miRNAs such as hsa-miR-214-3p and hsa-miR-195-5p to regulate the expression, respectively, of PPARGC1A and CCNE1 in hepatocellular carcinoma and breast cancer." (PMID 35322101, 2022). "This key finding highlights a critical and unique role of CCNE1 for survival and expansion of malignant hepatoma cells in a CDK2-independent manner in vivo, which until now were only hypothesised from in vitro observations." (PMID 34830835, 2021). "Further, suppression of NF90 delays cell cycle progress and cell growth in human hepatocellular carcinoma (HCC) cell lines through binding to the 3′-UTR of Cyclin E1 mRNA, and reduces the sensitivity of HCC cells to the roscovitine, a CDK inhibitor that is applied in II experiments." (PMID 29449553, 2018). "Moreover, miR-7 was shown to arrest cell cycle in G1 phase by directly targeting CCNE1 in human hepatocellular carcinoma cells." (PMID 29614984, 2018). "As ARID2 induces cyclin D1 and cyclin E1 repression, thereby inhibiting the proliferation of hepatoma cells, this protein may be critical for the suppression of HCC tumorigenesis in vivo." (PMID 27351279, 2016). "In addition, CCNE1 inhibition was shown to sensitise hepatoma cells to regorafenib." (PMID 34830835, 2021).
hepatocellular carcinoma (continued). "The potency of therapeutic CCNE1 inhibition on parenchymal tumour cell growth, stemness and invasion capacity should therefore be first addressed in 3D culture systems such as tumour spheres, hydrogel microspheres or organoids of hepatoma cells or patient-derived xenograft." (PMID 34830835, 2021). "In hepatocellular carcinoma, the insertion of hepatitis B virus enhancers into the host genome activates adjacent genes, such as TERT, KMT2B, and cyclin E1 (CCNE1)." (PMID 40032852, 2025). "CHEK1, CDC25A, and CCNE1, together with CCND1, CCND3, CDK4, CDK6, BTRC, E2F3, and FOXK1, were previously identified as the targets of miR‐497∼195 cluster in hepatocellular carcinoma." (PMID 40548926, 2025). "TTN‐AS1 also weakened the inhibition of apoptosis of hepatocellular carcinoma by sponging miR‐16‐5p expression, regulating the PTEN/Akt signaling pathway, and enhancing cyclin E1 expression." (PMID 37528740, 2023). "In our study, EB inhibited cell proliferation by blocking the cell cycle of hepatic carcinoma cells at the S phase, and its specific mechanism involved downregulation of the expressions of CDK2 and cyclin E1." (PMID 35866605, 2022). "Recently, we identified CCNE1 and CDK2 as key factors for the initiation of hepatocellular carcinoma (HCC)." (PMID 34830835, 2021). "In European and a few Japanese hepatocellular carcinoma (HCC) patients, it has been shown that AAV strains similar to AAV2 or AAV13 have the potential to integrate into genes including CCNA2 and CCNE1, contributing to oncogenesis." (PMID 34763675, 2021). "It has been demonstrated that miR-7 can inhibit cancer progression by suppressing CCNE1 and PIK3CD in hepatocellular carcinoma (HCC)." (PMID 30126353, 2018). "It reported that has-miR-195-497 cluster was intracellular antagonists of BMP signaling pathway in bone cells in and targeting cell cycle proteins CDK6, CCNE1, CDC25A and CDK4 to regulated cell proliferation in human hepatocellular carcinoma cells." (PMID 27384321, 2016). "Previous research suggested that expression of CCNE1 and CCNE2 could synergistically affect the overall survival in hepatocellular carcinoma (HCC) patients and HCC progression requires the expression of any E-cyclin." (PMID 38244572, 2024). "Furthermore, exosome RNPs showed solid therapeutic potential in acute liver injury, chronic liver fibrosis, and hepatocellular carcinoma mouse models by targeting PUMA, CcnE1, and KAT5, respectively." (PMID 37166046, 2023). "MCM7 inhibition led to a decrease in the esophagus and hepatocellular carcinomas viability, colony-forming ability, and migration capacity due to reducing phosphorylation of AKT1 and mTOR proteins with decreasing CDK1, CCNE1, and CCNE2 expression levels." (PMID 37529110, 2023). "Based on these findings, a potential miR-497-mRNA or miR-1246-mRNA regulatory network can be established, namely, miR-497-ARL2/UBE2Q1/PHF19/APLN/CHEK1/CASK/SUCO/CCNE1/KIF23, or miR-1246-AUTS2/SLAIN1, which contributes to the occurrence and development of hepatocellular carcinoma." (PMID 34163524, 2021). "In contrast to cyclin E1, the expression of cyclin D1 was not significantly changed in both hepatoma cell lines." (PMID 28720813, 2017). "Further, constitutive CCNE1 overexpression in fallopian tube secretory epithelial cells induced DNA damage, replication stress and CIN that corresponded with cellular transformation, while doxycycline induced overexpression in mice induced DNA damage, CIN and hepatocellular carcinoma." (PMID 32106628, 2020). "In addition, restoring ARID2 expression in hepatoma cells suppressed cell growth and tumor progression in mice while ARID2 inhibition resulted in upregulation of cell cycle proteins such as cyclin D1 and cyclin E1, suggesting a tumor suppressive role for ARID2 in HCC." (PMID 31056726, 2019).
hepatocellular carcinoma (continued). "We next examined if the absence of Ccne1 in HSCs may affect the expression of genes encoding albumin (Alb), α-fetoprotein (Afp), and CD133 (Prom1), which are established markers for hepatocytes (Alb), de-differentiated hepatoma cells (Afp) or liver cancer stem cells (Prom1)." (PMID 37620309, 2023).
gastric cancer (42 papers, 2011 to 2025). A primary or metastatic malignant neoplasm involving the stomach. "In a small cohort of patients with resected gastric cancer, CCNE1 overexpression was associated with worse disease-free survival." (PMID 38717153, 2024). "CCNE1 amplification is found in 11–12% of gastric cancers, and it was suggested to be associated with liver metastasis in gastric carcinoma." (PMID 37131253, 2023). "In good agreement, previous studies described that amplification of CCNE1 was associated with liver metastasis of gastric cancer subtypes and that silencing of CCNE1 resulted in reduced invasion and migration capabilities in cholangiocarcinoma." (PMID 34830835, 2021). "An association of CCNE1 amplification with DNA hypomethylation was previously reported in stomach cancer." (PMID 32213861, 2020). "Another common alteration in gastric cancer is the perturbation of the cell cycle control via the over expression of Cyclin E1, which is associated with tumour aggressiveness and lymph node metastasis." (PMID 21418558, 2011). "Overall, this study demonstrates that CCNE1 amplification is associated with a distinct molecular profile in gastric cancer and may impact response to therapy, including targeted therapy and/or immunotherapy." (PMID 38717153, 2024). "In addition, the histologic makeup of the study population affects the overall frequency of CCNE1 amplification, which is more likely to be associated with intestinal-type gastric cancer than diffuse type." (PMID 38717153, 2024). "Besides, it was also revealed that upregulated Cyclin E1 is highly associated gastric cancer development and liver metastasis." (PMID 33390953, 2020). "A novel oncogene CCNE1 (cyclin E) is considered to be associated with the development of various tumor types, its role in gastric carcinoma (GC) is little studied and the effect of CCNE1 on chemotherapy also remains unclear." (PMID 31072916, 2019). "The downregulation of CCNE1 expression inhibits cell proliferation and increases the sensitivity of gastric cancer cells to cisplatin." (PMID 40076877, 2025). "Independently, miR‐195‐5p has been described as a regulator of the CHEK1 gene in non‐small cell lung and gastric carcinoma, and CCNE1 in glioma." (PMID 40548926, 2025). "While CCNE1 amplification has been previously identified in gastric cancer, its clinical relevance in a real-world setting has been largely uncharacterized." (PMID 38717153, 2024). "In this study, we utilized comprehensive molecular profiling to define the incidence and molecular features of CCNE1-amplified gastric cancer, as well as implications on treatment outcome." (PMID 38717153, 2024). "The association of CCNE1 amplification with metastases is consistent with other data suggesting that patients with CCNE1-amplified gastric cancer are more likely to have liver metastases." (PMID 38717153, 2024). "Previous studies identified a correlation between CCNE1 amplification and increased liver metastases as well as poor survival in select cohorts of patients with gastric cancer." (PMID 38717153, 2024). "Real-world survival analysis demonstrated that patients with CCNE1-amplified gastric cancer had worse survival after trastuzumab for HER2-positive tumors, but better survival after immunotherapy." (PMID 38717153, 2024). "CCNE1 amplification also occurs commonly in gastric carcinoma, so we tested the cell line MKN1 and found it was similarly sensitive to INX-315 (IC50 44 nmol/L) and insensitive to palbociclib." (PMID 38047585, 2024). "CCNE1 amplification is correlated to metastasis in gastric carcinoma and gynecologic high‐grade serous carcinoma, poor prognosis in lung adenocarcinoma." (PMID 36653904, 2023). "In HER2-positive gastric cancer, patients with CCNE1 amplification have a poorer benefit than the patients without CCNE1 amplification." (PMID 36699065, 2022).
gastric cancer (continued). "It was shown that silencing KRT inhibited the proliferation, migration, and invasion of gastric cancer cells, induced apoptosis, and stalled the gastric cancer cell cycle at the G1/S phase by decreasing the expression of cyclin E1 and cyclin D." (PMID 36467074, 2022). "We found that GCA shares some common oncogene focal amplifications with both gastric cancer and esophageal cancer including CCNE1, EGFR, and MYC." (PMID 34764264, 2021). "The top two ranking oncogene focal amplifications, ERBB2 and CCNE1, were the same in both gastric cancer and GCAs." (PMID 34764264, 2021). "The results revealed that the expression of Cyclin E1 was remarkably decreased in both mRNA and protein levels after BD treatment in gastric cancer cells, but was recovered in some extent after LINC01667 restoration." (PMID 33390953, 2020). "In summary, we identify that BD inhibits the proliferation of gastric cancer cells through the LINC01667/miR-138-5p/Cyclin E1 pathway." (PMID 33390953, 2020). "CCNE1 is found to be an oncogene in multiple cancer types, such as gastric cancer, colorectal cancer, prostate cancer, and NSCLC." (PMID 33033491, 2020). "Cyclin E overexpression as a result of CCNE1 amplification is a critical driver of genomic instability in gastric cancer, but its clinical implication is largely unknown." (PMID 38717153, 2024). "However, patients with HER2-positive gastric cancer and concurrent CCNE1 amplification experienced poorer prognosis after receiving trastuzumab than those without concurrent CCNE1 amplification." (PMID 38717153, 2024). "In addition, CCNE1-MTOR (gastric cancer) and SMO-MDM2 (skin cancer) are found to be putative SL interactions according to the shRNA data." (PMID 37863651, 2024). "Analysis of CIN-type EG adenocarcinomas from TCGA revealed that immune-cold tumors with decreased CD8+ T-cell infiltration are enriched for CCNE1 amplifications, suggesting that CCNE1 amplification may also promote immune resistance in gastric cancer." (PMID 38717153, 2024). "In addition, previous studies in gastric cancer showed that CircDENND2A can promote the progression of non-small-cell lung cancer by regulating the CCNE1 signaling pathway." (PMID 39591374, 2024). "The most frequently amplified oncogenes in gastric cancers, including MYC, ERBB2 (encoding for HER2), and CCNE1 (encoding for cyclin E), showed higher prevalence in the higher CDX2-expressing group, which was statistically significant for MYC (Fisher’s exact test p = 0.008)." (PMID 39768557, 2024). "In addition, the ablation of CDCA5 inhibited gastric cancer cell proliferation via downregulating Cyclin E1 expression." (PMID 36741311, 2023). "It is believed that CCNE1 amplification may be related to the resistance of HER2 monoclonal antibody and is associated with poor prognosis in HER2-positive gastric cancer." (PMID 36699065, 2022). "Interestingly, four of the identified key genes (CDK6, MCM2, PRKDC, and CCNE1) are on the cell cycle pathway, underscoring the importance of this process in gastric cancer." (PMID 28603669, 2017). "High levels of CCNE1 have been shown to be frequently associated with early gastric cancer and metastasis but expression levels do not correlate with survival." (PMID 21781349, 2011). "Future studies such as single-cell RNA sequencing, spatial transcriptomics, or quantitative immunofluorescence may further define the immune cell composition and localization in CCNE1-amplified gastric cancer, and how the distinct tumor microenvironment may impact response to therapy." (PMID 38717153, 2024).